GATA1 (GATA binding protein 1)
Diseases named in the same sentence as GATA1 in open-access papers (continued):
Sharing a sentence is not in itself a finding about the gene and the disease.
lung adenocarcinoma (6 papers, 2017 to 2024). A carcinoma that arises from the lung and is characterized by the presence of malignant glandular epithelial cells. "Expression analysis in more patients is also required to elucidate the function of GATA-1 and mutated GATA-1 in lung adenocarcinoma." (PMID 28566697, 2017). "Considering GATA-1s was shown previously to be less functional than the full-length GATA-117, these results demonstrated that suppression of endogenous GATA-1 gene expression might be associated with the up-regulation of IRF-3 in lung adenocarcinoma." (PMID 28566697, 2017). "We then changed the search term into “GATA-1” and compared datasets representing lung adenocarcinoma and Cancer vs. Normal Analysis." (PMID 28566697, 2017). "The Oncomine database was queried for IRF-3 and GATA-1 expression in lung adenocarcinoma and normal tissue." (PMID 28566697, 2017). "In contrast to the effect of suppression, GATA-1 over-expression caused a dramatic decrease of the promoter activity and protein expression of IRF-3 in different lung adenocarcinoma cell lines." (PMID 28566697, 2017). "We conducted cDNA microarray analysis by using the Oncomine database to explore gene expression of IRF-3 and GATA-1 in lung adenocarcinoma." (PMID 28566697, 2017). "We found elevated IRF-3 and decreased GATA-1 gene expression in lung adenocarcinoma in Oncomine database." (PMID 28566697, 2017). "In Oncomine analysis, Bhattacharjee Lung and Selamat Lung datasets showed that GATA-1 gene expression was decreased in lung adenocarcinoma in comparison with normal lung tissues." (PMID 28566697, 2017). "Lower expression of GATA-1 RNA was found in lung adenocarcinoma compared with normal tissues in Bhattacharjee Lung and Selamat Lung datasets." (PMID 28566697, 2017). "In this study, we found a specific GATA-1 binding site in IRF-3 promoter and observed aberrant gene expression of IRF-3 and GATA-1 in lung adenocarcinoma." (PMID 28566697, 2017). "Only one study by Wang 37 reported that suppression of endogenous GATA-1 gene expression was found in lung adenocarcinoma, which might be connected with the upregulation of IRF-3." (PMID 34093794, 2021). "Additionally, higher IRF-3 gene expression was observed in human lung adenocarcinoma, accompanied by aberrant GATA-1 protein expression." (PMID 28566697, 2017). "Taken together, we conclude that reduced GATA-1 could be responsible for the upregulation of IRF-3 in lung adenocarcinoma cells through binding with a specific domain of IRF-3 promoter." (PMID 28566697, 2017). "We also observed aberrant expression of GATA-1 in lung adenocarcinoma." (PMID 28566697, 2017). "In one tissue from a patient with lung adenocarcinoma, a western blot experiment showed a lack of full-length GATA-1 protein expression and a weak signal for GATA-1 mutation (GATA-1s)." (PMID 28566697, 2017). "Additionally, down-regulated expression of GATA-1 protein might be responsible for the up-regulation of IRF-3 expression in lung adenocarcinoma cell lines which is in accordance with the observation in our Oncomine analysis and lung adenocarcinoma samples." (PMID 28566697, 2017). "Due to few samples in this study, it is arbitrary to take a conclusion that GATA-1 was under-expressed and replaced by GATA-1s in lung adenocarcinoma." (PMID 28566697, 2017). "In summary, our study implied that TSA enhanced IRF-3 gene expression through increased GATA-1 recruitment to IRF-3 promoter and the acetylation level of GATA-1 in lung adenocarcinoma A549 cells." (PMID 29100282, 2017). "We further investigated their relationship in lung adenocarcinoma cell lines and found that suppression of endogeneous GATA-1 increased the IRF-3 transcriptional activity through the GATA-1 element in the IRF-3 promoter." (PMID 28566697, 2017).
lung adenocarcinoma (continued). "We further analyzed the relationship of GATA-1 and IRF-3 expression in lung adenocarcinoma cell lines and found that inhibition of GATA-1 by siRNA increased the promoter activity, mRNA and protein levels of IRF-3, while over-expression of GATA-1 down-regulated IRF-3 gene expression." (PMID 28566697, 2017). "In our experiments with human lung adenocarcinoma samples, we observed a higher protein level of GATA-1s and lack of full-length GATA-1 protein in lung adenocarcinoma tissue." (PMID 28566697, 2017). "Thus, we addressed this question and found that suppressed endogenous GATA-1 protein expression increased the promoter activity, mRNA and protein of IRF-3 gene in lung adenocarcinoma cell lines." (PMID 28566697, 2017). "In a tissue of another patient with lung adenocarcinoma, GATA-1s was highly expressed but the full-length GATA-1 was nearly absent." (PMID 28566697, 2017).
lung carcinoma (6 papers, 2014 to 2024). "GATA1 has been linked to survival time in lung cancer patients." (PMID 35743687, 2022). "This study further validated that the low expression of GATA1 means shorter survival in lung cancer." (PMID 35743687, 2022). "When cross-analyzing ADAMTS8 based on the levels of GATA1 in survival time, lung cancer patients with low-level ADAMTS8 survived for a shorter period when compared with high-level based on low GATA1 but not LMO2 expression." (PMID 35743687, 2022). "The expression levels of GATA1 and LMO2 were low and associated with advanced lymph node metastasis and staging in lung cancer (left two panels)." (PMID 35743687, 2022). "The aberrant expression or DNA modification of GATA-2, GATA-4, GATA-5, and GATA-6 was found in lung cancer, but GATA-1 gene expression is seldom reported in LADC." (PMID 29100282, 2017). "To explore the expression of GATA-1 in lung cancer, we detected GATA-1 protein expression in human LADC tissue and A549 cells." (PMID 29100282, 2017). "The deficiency of GATA-1 in the tumor was accompanied by high expression of IRF-3, suggesting the potential relationship between decreased GATA-1 and increased IRF-3 in lung cancer cells." (PMID 28566697, 2017). "Gene sequencing is required to confirm the alternative splicing of GATA-1 in patients with lung cancer." (PMID 28566697, 2017). "GATA1, GATA4 and GATA5 were exceptionally downregulated in lung cancer cell lines, including SCLC and NSCLC." (PMID 34093794, 2021). "However, only GATA1 and LMO2 showed more than a two-fold change between normal parts and tumor parts in lung cancer." (PMID 35743687, 2022). "However, the relationship between GATA2 or GATA1 and the clinical and prognosis of lung cancer has not been clarified." (PMID 34093794, 2021).
myeloproliferative disorder (6 papers, 2021 to 2024). A clonal hematopoietic stem cell disorder, characterized by proliferation in the bone marrow of one or more of the myeloid (i.e., granulocytic, erythroid, megakaryocytic, and mast cell) lineages. "Myeloproliferative disorders associated with DS are the result of a multistep clonal process, with emerging genetic events that co-operate with mutant GATA1 clones." (PMID 35805057, 2022). "First, the acquisition of mutations in the GATA1 transcription factor gives rise to a transient myeloproliferative disorder (TMD) in DS newborns." (PMID 34439298, 2021). "These mice develop a progressive myeloproliferative disorder that has many features of myelofibrosis after 1 year of life and reduced levels of GATA-1 have also been demonstrated in the megakaryocytes of patients with IMF." (PMID 35887218, 2022).
pancreatic cancer (6 papers, 2010 to 2025). "Taken together, we demonstrated that GATA1 is a new predictive marker for prognosis and gemcitabine resistance in pancreatic cancer patients." (PMID 31093285, 2019). "Afterwards, we investigated the effect of GATA1 on gemcitabine resistance in pancreatic cancer cells." (PMID 31093285, 2019). "Taken together, our results indicate that GATA1 is a novel marker and potential target for pancreatic cancer." (PMID 31093285, 2019). "Here, we demonstrate that the transcription factor GATA binding protein 1 (GATA1) promotes gemcitabine resistance in pancreatic cancer through antiapoptotic pathway." (PMID 31093285, 2019). "GATA1 overexpression markedly promoted tumor growth, whereas knockdown of Bcl-XL dramatically inhibited pancreatic tumor growth, and Bcl-XL knockdown offset GATA1 mediated tumor growth." (PMID 31093285, 2019). "Here, we found a novel function of GATA1 in gemcitabine resistance in pancreatic cancer." (PMID 31093285, 2019). "Since GATA1 and Bcl-XL are both involved in gemcitabine resistance of pancreatic cancer cells, and Bcl-XL is a target gene of GATA1, we tested whether GATA1 promotes gemcitabine resistance through regulating Bcl-XL level with cell viability assay and colony formation assay." (PMID 31093285, 2019). "In pancreatic cancer, HDAC5 inhibits the binding of GATA1 to the promoter region of the downstream gene PLA2G4A by deacetylating the transcription factor GATA1." (PMID 40781327, 2025). "We speculate that GATA1 confers gemcitabine resistance in pancreatic cancer not only by activating Bcl-XL, but also by retaining proliferative potential of PDAC cancer following treatment with gemcitabine." (PMID 31093285, 2019).
chronic myeloid leukemia (5 papers, 2014 to 2023). "For instance, using data from K562 cell line, we show the recovery of a large-scale enhancer regulatory network, depending on HDAC2 and GATA1 rescued peaks, whose components are involved in Chronic Myeloid Leukemia (CML) and several cancer-associated processes." (PMID 37286963, 2023). "Of note, studies from the Zon laboratory showed BMP2 treatment of K562 and U937 recruited phosphor SMAD1 with lineage specific factors (erythroid factor GATA1 in K562 cells derived from chronic myelogenous leukemia in erythroid blast crisis and CEBPA in U937 myelomonocytic cells)." (PMID 25544748, 2014). "EP300 is abundant at super-enhancers and coincident with sites of GATA1 and MYC occupancy in chronic myeloid leukemia (CML) cell line K562." (PMID 36831561, 2023). "CBP/p300 bromodomain inhibition blocks GATA1 and MYC oncogene expression and induces chronic myeloid leukemia and lymphoma cell cycle arrest and growth inhibition." (PMID 35836809, 2022).
malaria (5 papers, 2017 to 2023). Malaria is a serious and sometimes fatal disease caused by a parasite that commonly infects a certain type of mosquito which feeds on humans. "The low level of GATA-1 expression may be responsible for reduced RBC formation in malaria-infected animals." (PMID 33298881, 2020). "Future studies should examine the factors that influence the function of GATA1/GATA2 during malaria since it is clear that a variety of intermediate molecules besides those described here could also affect each protein’s function." (PMID 28938907, 2017). "A number of variant SNPs have been identified in this gene, mostly in Linkage Disequilibrium (LD), and though it is not clear whether all these SNPs play a role in protection against severe malaria, one of them was shown to disrupt a GATA-1 site in the promoter of the gene." (PMID 38173794, 2023). "Since GATA-1 is a key erythroid cell differentiation factor, the low level of GATA-1 expression may be responsible for reduced RBC formation in malaria-infected animals." (PMID 35735506, 2022). "Here we show that infusion of MSCs isolated from malaria-infected mice protects recipient animals from malaria infection, induces CD34+ cells in secondary lymphoid organs, restores erythropoiesis by upregulation of GATA-1, and restores T cells by lymphopoiesis." (PMID 33298881, 2020). "In this study, it was shown that GATA1 and GATA2, two master regulators of erythropoiesis, may not function appropriately during acute malaria." (PMID 28938907, 2017).
trisomy 21 (5 papers, 2019 to 2024). A chromosomal disorder consisting of the presence of an extra chromosome 21. "The preleukemic, myelodysplastic phase of TAM in blasts bearing trisomy 21 is driven by variants in the key hematopoietic transcription factor GATA1 gene." (PMID 39457216, 2024). "In the second case, foetal hydrops was detected at 31 weeks of gestation, and trisomy 21 was diagnosed by umbilical venipuncture, and the heterozygous variant of the GATA1 gene c.49dupC was reported for the first time." (PMID 37858167, 2023). "The unique cooperation between GATA1 mutations and trisomy 21 in the evolution of TAM has been approved by the fact that GATA1 mutations have, to date, been discovered in nearly all patients with TAM and ML–DS." (PMID 37444375, 2023). "In the context of trisomy 21, GATA1 mutations are strengthened and become sufficient to lead to TAM and/or ML-DS, whereas these mutations are not detected when TAM resolves." (PMID 37444375, 2023). "In about 1 of 10 DS infants, trisomy 21 and GATA1 mutation together induce TAM, characterized by an abnormally high population of myeloblasts in the peripheral blood." (PMID 33102613, 2020). "GATA1 mutations were strictly linked to the context of trisomy 21 in DS patients and this condition provided the cellular setting for the persistence and eventual transformation of GATA1 mutant cells." (PMID 30873408, 2019). "It is generally accepted that the GATA1 mutations and trisomy 21 cooperate in causing TAM." (PMID 37858167, 2023).
bleeding disorders (4 papers, 2015 to 2025). "The proper expression of PF4, driven by GATA1, is necessary for maintaining platelet function and preventing bleeding disorders." (PMID 40937321, 2025). "A handful of the candidate defects were present in genes that had previously been associated with platelet bleeding disorders, including P2RY12, VPS33B, GATA1, ANKRD26, HPS1, VWF, and LYST22." (PMID 25556537, 2015). "The fact that neither parent of the index patient suffered from a bleeding disorder suggested autosomal or X-linked recessive inheritance, a criterion that was only met by the GATA1 variant c.886A>C p.(Thr296Pro)." (PMID 36231035, 2022). "Since she is not affected by a bleeding disorder, we assumed a random X-inactivation, and thus only ≈50% varied GATA1 in the mother." (PMID 36231035, 2022).
macrocytic anemia (4 papers, 2016 to 2023). Anemia that is characterized by increased red blood cell volume. "In addition to macrocytic anemia, this patient showed moderate neutropenia, and aberrant megakaryocyte thrombopoiesis, similar to GATA1-linked DBS." (PMID 36845397, 2023).
neutropenia (4 papers, 2021 to 2023). A decrease in the number of neutrophils found in the blood. "DBS caused by GATA1 deficiency has different phenotypic characteristics, including abnormal erythropoiesis and megakaryocytes, and neutropenia." (PMID 36845397, 2023).
prostate carcinoma (4 papers, 2008 to 2020). A carcinoma that arises from epithelial cells of the prostate gland. "Evolutionary conserved transcription factor binding sites (TFBS) recognized by WT1, EGR1, SP1, SP2, AP2 and GATA1 were identified in the promoters of 24 differentially expressed prostate cancer genes from eight mammalian species." (PMID 18631392, 2008). "For both promoters and enhancers we also identified a subset of disruptive variants that target response elements for factors of special interest to prostate cancer, namely AR, FOXA1, NKX3-1, TCF7L2, MYC, GATA1 and GATA3." (PMID 24497837, 2014).
asthma (3 papers, 2021 to 2025). "High GATA1 expression was associated with pathways related to allograft rejection and asthma." (PMID 41316541, 2025).
atherosclerosis (3 papers, 2016 to 2023). A disease characterized by the build-up of fatty material and calcium deposition in the arterial wall resulting in partial or complete occlusion of the arterial lumen. "The transcription factors RUNX1, GATA1, STAT3, NFκB, and PPAR have been widely reported to play key roles in the pathophysiology of platelet hyper-reactivity, thrombosis, and atherosclerosis." (PMID 36969155, 2023). "In addition, genes predicted to be targeted by the miR-17-5p, not previously associated with atherosclerosis, include ARID4B, E2F, GATA1, MEF2D, NR1I2, PURA, and RBL2." (PMID 36859458, 2023).
erythroblastic leukemia (3 papers, 2021 to 2024). "In female mice heterozygous for both the Gata1.05 and wild-type alleles, we observed a predisposition to erythroblastic leukemia three to six months after birth." (PMID 38409047, 2024).
Macrothrombocytopenia (3 papers, 2016 to 2025). "Freson and coworkers also reported for two patients with macrothrombocytopenia that the GATA1 N-terminal zinc finger variants D218Y/G suppress NBEAL2 RNA and protein expression, leading to paucity of platelet α-granules." (PMID 36231035, 2022). "A number of distinct pathogenic GATA1 variants have been identified within the first N-terminal zinc finger domain of GATA1 associated with variable macrothrombocytopenia, platelet aggregation defects, and α-granule deficiency." (PMID 36231035, 2022). "Selective loss of Gata1 expression in adult mice results in macrothrombocytopenia with platelet dysfunction, characterized by an excess of immature megakaryocytes." (PMID 27152938, 2016). "Ultrastructural analysis of platelets from a patient with the GATA1 R216Q variant, causing macrothrombocytopenia with β-thalassemia, demonstrated a severe reduction of δ-granules and a paucity of α-granules, whereas macrothrombocytes presented with giant α-granules." (PMID 36231035, 2022). "Mice with targeted mutations on the Gata1 promoter affecting its expression, such as Gata-1.05/X female mice and ΔneoΔHS mice, display severe macrothrombocytopenia, an increased proliferation of megakaryocytes, and platelets with a defective response to collagen and vWF." (PMID 27152938, 2016). "Comparable to the ΔneoΔHS and Gata1.05 mouse models, Gata1cKOMK mice show severe macrothrombocytopenia accompanied by platelet dysfunction, while in Gata1cKOMK mice the red blood cells and white blood cell counts are unaffected." (PMID 27152938, 2016). "Although G6PD levels were very low, the history of transfusions and macrothrombocytopenia prompted preliminary testing for a GATA1 mutation, which was negative." (PMID 40941697, 2025). "Thus, the symptoms of the index (macrothrombocytopenia, platelet dysfunction, and mild dyserythropoiesis) and his daughter (similar symptoms, but normal platelet count) are in good agreement with a GATA1 defect in the C-terminal part of the protein." (PMID 36231035, 2022). "All disorders have in common mutations mostly located in the amino (N)-zinc finger region of GATA1, which might influence either DNA binding directly and/or the interaction with Friend of Gata1 (FOG1), leading to macrothrombocytopenia." (PMID 27152938, 2016).
megakaryoblastic leukemia (3 papers, 2017 to 2022). "GATA1 mutation is generally required for tumor initiation in megakaryoblastic leukemia, as defined by a transient loss of proliferative control." (PMID 36037342, 2022). "The combination treatment decreased GATA1 levels to a greater extent than did either agent alone in TF-1a cells and in MOLM-16, a megakaryoblastic leukemia cell line." (PMID 28892104, 2017).
Splenomegaly (3 papers, 2018 to 2021). Abnormal increased size of the spleen. "GATA-1 is a transcriptional modulator (activator or repressor) for erythroid development, differentiation and often found upregulated in splenomegaly." (PMID 31170255, 2019).
stem cell leukemia (3 papers, 2018 to 2023). "In erythroid differentiation, core transcriptional networks play crucial roles, which include gata binding protein 1 (GATA1), T-cell acute lymphoblastic leukemia/stem cell leukemia (TAL1/SCL), Krüppel-Like Factor 1 (KLF1), LIM domain only 2 (LMO2), and LIM domain binding protein 1 (LDB1)." (PMID 37296674, 2023).